CHEK2 (checkpoint kinase 2)
Diseases named in the same sentence as CHEK2 in open-access papers (continued):
Sharing a sentence is not in itself a finding about the gene and the disease.
Fanconi anemia (23 papers, 2008 to 2025). Fanconi anemia (FA) is a hereditary DNA repair disorder characterized by progressive pancytopenia with bone marrow failure, variable congenital malformations and predisposition to develop hematological or solid tumors. "Two genes in the HRR pathway, RAD51, and XRCC2, cell cycle regulation (CHEK2), and Fanconi Anemia (UBE2T) were significantly upregulated in Groups 3 and 4 (p = 0.042, p = 0.0042, p = 0.021, and p = 0.023, respectively)." (PMID 37334114, 2023). "Additionally, significant roles are played by PALB2, ATM, ATR, CHEK1, CHEK2, RAD51, and genes linked to Fanconi anaemia." (PMID 40069561, 2025). "CHEK2 is involved in the DNA damage repair response Fanconi anemia (FA)-BRCA pathway." (PMID 31349801, 2019). "HRR alterations involve Fanconi anemia genes (PALB2, FANCA, FANCL, FANCI, FANCC), core RAD genes (RAD50, RAD51, RAD51B, RAD51C) as well as DNA damage response genes (ATM, ATR, CHEK1, CHEK2)." (PMID 36531003, 2022). "These genes include the Fanconi anemia pathway genes: FANCA, PALB2, BRIP1, RAD51C and XRCC2 and non-Fanconi anemia genes: ATM, CHEK2, NBN, RAD50, RAD51B, and RAD51D." (PMID 28202063, 2017). "Some of these non-core genes include ARID1A, ATM, RAD51, CHEK2, and the Fanconi anemia genes." (PMID 39860372, 2025). "Among DNA repair genes, we detected a high presence of members of the Fanconi Anemia Complementation Group (FANCC, FANCD2, FANCG, FANCA, and FANCE), which participate in homologous recombination DNA repair, and genes involved in double-strand break repair (BRCA2, BRIP1, BARD, BLM, CHEK2, and PALB2)." (PMID 30487452, 2018).
glioblastoma (23 papers, 2010 to 2026). The most malignant astrocytic tumor (WHO grade IV). "Mutations in the CHEK2 gene have been identified in glioblastomas and glial CNS tumors in children." (PMID 40867242, 2025). "Germline CHEK2 mutations have also been observed in medulloblastoma and primary glioblastomas." (PMID 35281821, 2022). "In glioblastoma patients, copy number loss of the genes encoding the ATM/Chk2 and ATR/Chk1 pathways frequently occurs, with heterozygous loss of CHEK2 being the most common occurrence." (PMID 39227895, 2024). "Regardless, no prior studies have specifically reported germline CHEK2 alterations in subependymal giant cell tumors or medulloblastomas, although CHEK2 germline alterations have been identified in patients with glioblastoma and other pediatric brain tumors." (PMID 36980535, 2023). "In addition, the co-expression of APEX1 and CHEK2 genes was positively correlated in the TCGA glioblastoma data set (r = 0.198, p = 3.6.10–6, n = 540; Tumor Glioblastoma-TCGA-540-MAS5.0-u133a dataset; R2: Microarray Analysis and Visualization Platform)." (PMID 28852018, 2017). "For example, in glioblastoma (GBM), inhibition of checkpoint kinase 1 (Chk1) and checkpoint kinase 2 (Chk2) activity decreased its resistance to radiotherapy." (PMID 35205721, 2022). "In addition, higher expression levels of MMP9, TERT, VEGFA, ZDHHC18, CHEK2, and ADM elevate the probability of predicting glioblastoma." (PMID 40867242, 2025).
sarcoma (22 papers, 2014 to 2025). A usually aggressive malignant neoplasm of the soft tissue or bone. "Secondly, while four known sarcoma-associated pathogenic germline variants were detected, we also detected four CHEK2 germline variants with currently unknown relevance in sarcoma tumorigenesis." (PMID 35053600, 2022). "The clinical relevance of CHEK2 germline mutations in sarcoma patients is currently unknown." (PMID 35053600, 2022). "The next most frequently mutated genes included CHEK2 (1.4%), ATM (1.2%), and MUTYH (1.2%), with the remaining DDR pathway genes altered in less than 1% of all sarcomas." (PMID 40563612, 2025). "The CHEK2 variant p.(Thr367MetfsTer15) has also been associated with an increased risk for sarcomas in a large Danish study, although this association was not significant after adjustment for multiple comparisons." (PMID 39669616, 2024). "Moreover, confirmation of this sarcoma as part of the CHEK2 cancer spectrum could inform genetic testing recommendations for patients with DFSP." (PMID 39669616, 2024). "None of the three CHEK2 carriers had a second hit in the tumor, suggesting a weak link to sarcoma." (PMID 39594770, 2024).
hepatocellular carcinoma (20 papers, 2008 to 2026). A malignant tumor that arises from hepatocytes. "CHEK2 regulates mitochondrial metabolism and is highly expressed in hepatocellular carcinoma patients." (PMID 38081888, 2023). "Using a model of chemically induced hepatocellular carcinoma in mouse liver, we comparatively analyzed the dynamics of transcript levels for several genes (BRCA1, BRCA2, CHEK1, CHEK2, ATM, CDK12) in paired samples of normal and tumor tissue over a 24-h PMI using RT-qPCR." (PMID 42073491, 2026). "In cases of hepatocellular carcinoma (HCC), overexpression of TIM exerted oncogenic function through CHEK2 and eukaryotic elongation factor 1A2 (EEF1A2)." (PMID 32499870, 2020).
endometrial cancer (18 papers, 2015 to 2025). Primary or metastatic malignant neoplasm involving the endometrium (mucous membrane that lines the endometrial cavity). "While mutation in CHEK2 has been reported in patients with endometrial cancers, and because of that, it is worth considering if CHEK2 mutation affected our patient’s uterine polyps." (PMID 32570972, 2020). "The CHK2 protein is encoded by CHEK2, a gene that is frequently mutated in endometrial cancer." (PMID 39766121, 2024). "The CHEK2 variant identified (c.507delT) has been associated with ovarian and endometrial cancers." (PMID 38476463, 2023). "Based on limited data, the evidence does not support the relationship of CHEK2 mutations with a significantly higher risk of endometrial cancer." (PMID 38136276, 2023). "The p.Arg95Ter CHEK2 variant, resulting in a missense alteration, reported in Individual 5, was previously reported in endometrial carcinoma and choriocarcinoma, but never previously in MDS." (PMID 36980535, 2023). "The pathogenicity of the NBN and CHEK2 mutations in this case remains unclear, and current literature has not specifically linked these mutations to endometrial cancer risk." (PMID 40356752, 2025).
lymphoma (18 papers, 2007 to 2026). A malignant (clonal) proliferation of B- lymphocytes or T- lymphocytes which involves the lymph nodes, bone marrow and/or extranodal sites. "CHEK2 kinase activity is also required for proper mitotic spindle assembly and chromosome stability, and CHEK2 deficient lymphoma cells are more sensitive to taxol." (PMID 25884806, 2015). "Mouse studies have shown that ATM or CHEK2 deficient mice often develop lymphoma." (PMID 40253392, 2025). "In lymphoma cells, pterostilbene was found to increase the level of CHEK2, a protein kinase known as an important mediator of the DNA damage checkpoint for phosphorylate proteins involved in DNA repair and cell cycle arrest." (PMID 36674631, 2023). "At Stage III cattle with lymphoma, only two integration sites were generated de novo in the intergenic region of Chr1, and the intron of the CHEK2 gene on Chr17 was significantly increased." (PMID 36329491, 2022). "CHEK2 alterations responsible for these low levels occur in a subset of aggressive lymphomas having a relatively high number of chromosomal imbalances." (PMID 17683622, 2007). "Germline mutations in CHEK2 (OMIM: 604373), in particular truncating mutations, are considered causative of Li Fraumeni (like) syndrome 2 (LFS2) (OMIM: 609265) and are associated with increased cancer risk, with lymphoma belonging to the disease spectrum of LFS59,60." (PMID 30926794, 2019).
breast and ovarian cancer (17 papers, 2014 to 2026). "One BRCA2 pathogenic variant carrier and one CHEK2 LP variant carrier met the testing criteria for HBOC syndrome." (PMID 40446793, 2025). "In conclusion, we detected a significantly high prevalence of PALB2, BARD1, and BLM mutations, with a low frequency of mutant CHEK2 in the current Japanese cohort of 568 patients with BRCA1/2 WT HBOC syndrome." (PMID 32566746, 2020).
osteosarcoma (15 papers, 2008 to 2025). A usually aggressive malignant bone-forming mesenchymal neoplasm, predominantly affecting adolescents and young adults. "Segregation studies were performed in the brother but not in his young son, who denied his consent, despite his previous diagnosis of osteosarcoma and the detection of the CHEK2 LP variant in his father." (PMID 32957588, 2020). "CHEK2 is considered a tumour suppressor and mutations of CHEK2 have been implicated in the pathogenesis of various types of familial as well as sporadic tumours, for example, the malignant bone tumour osteosarcoma." (PMID 18071362, 2008). "Case-52 (osteosarcoma, 11 yrs) showing no clinical features indicative of a CPS carried a maternally transmitted splice region variant in CHEK2 (LRG_302t1:c.444+3A>G)." (PMID 33840814, 2021). "Apart from G0/G1 arrest, piperine arrests osteosarcoma cells at G2/M phase of cell cycle through the downregulation of cyclin B1 and enhanced phosphorylation of cyclin-dependent kinase-1 (CDK1) and checkpoint kinase 2 (Chk2)." (PMID 29497610, 2018).
triple-negative breast carcinoma (15 papers, 2015 to 2023). An invasive breast carcinoma which is negative for expression of estrogen receptor (ER), progesterone receptor (PR), and human epidermal growth factor receptor 2 (HER2). "Age-specific distributions of oestrogen-receptor-negative and triple-negative breast cancer status for pathogenic variant carriers in these genes and CHEK2 and ATM were also incorporated." (PMID 36162851, 2022). "Consistent with that, no CHEK2 mutation carriers were observed in a previous analysis of 1824 triple negative breast cancer patients." (PMID 33919281, 2021). "Mutations in BRCA1 were most frequent in patients with triple-negative breast cancer (18.4%), and mutations in CHEK2 were most frequent in patients with hereditary non-triple-negative breast cancers (15.9%)." (PMID 26083025, 2015).
kidney cancer (14 papers, 2021 to 2024). Primary or metastatic malignant neoplasm involving the kidney. "CHEK2 mutations are known to increase breast, ovarian, thyroid, pancreas, colon, prostate, and kidney cancer risk, being considered a multiorgan cancer susceptibility gene, with moderate penetrance." (PMID 38367672, 2024). "Several studies show an association between pathogenic variants in CHEK2 and the hereditary risk of kidney cancer." (PMID 38002934, 2023). "Truncating CHEK2 mutations has been associated with kidney cancer patients in the clear cell carcinoma subgroup of Fuhrman Grade II disease." (PMID 34499690, 2021). "We observed truncating CHEK2 mutations were associated with kidney cancer patients with GII clear cell carcinoma." (PMID 34499690, 2021). "Survival of patients with kidney cancer; by variant alleles of CHEK2." (PMID 34499690, 2021). "Clinical characteristics of kidney cancers; by variant alleles of CHEK2." (PMID 34499690, 2021). "All the first primary cancer sites with significant familial risk may have common genetic and lifestyle-related risk factors with CRC, for example, CHEK2 mutation for breast, prostate and kidney cancers, alcohol intake for cancers in the upper aerodigestive tract and breast." (PMID 35982395, 2022). "This is not sufficient to propose a systematic cancer screening in carriers, or to include CHEK2 in kidney cancer gene panels." (PMID 38002934, 2023). "Afterwards, we analyzed the gene mutations in the high-risk and low-risk groups of the advanced kidney cancer and discovered the mutation of some genes, such as VHL, CHEK2, BAP1, PBRM1, which were closely related to RCC." (PMID 35739510, 2022). "Indeed, a large number of studies have been pointing out a possible connection between CHEK2 alteration and the onset of kidney cancer (especially renal cell carcinoma)." (PMID 37628581, 2023). "The 10-year survival for CHEK2 mutation carriers with kidney cancer 34% and for non-carriers 20% (p = 0.5)." (PMID 34499690, 2021). "In conclusion, this study reveals that CHEK2 does not appear to be associated with prognosis or grade of disease in either urothelial bladder cancer of kidney cancer." (PMID 34499690, 2021). "The purpose of this study was to compare the clinical characteristics and the survival of CHEK2 mutation positive and CHEK2 mutation negative patients diagnosed with bladder or kidney cancer." (PMID 34499690, 2021). "We found no impact of CHEK2 mutations on bladder or kidney cancer survival." (PMID 34499690, 2021). "In this study, we found no impact of CHEK2 mutations on bladder or kidney cancer survival." (PMID 34499690, 2021).
neuroblastoma (14 papers, 2007 to 2025). Neuroblastoma (NB) is the most common solid, extracranial childhood tumor. "In summary, the germline CHEK2 alterations presented in individuals with a diversity of tumor histologies, including one individual with concurrent Burkitt lymphoma and neuroblastoma." (PMID 36980535, 2023). "In an animal model study, daily high-dose ascorbate (4 g/kg) inhibited neuroblastoma growth, and tumors had increased activity of checkpoint kinase 2 (CHK2) and histone 2AX (H2AX)." (PMID 38274206, 2023). "CHEK2 was an independent prognostic factor of paediatric neuroblastoma in the TARGET, E-TABM-38 and GSE49710 datasets." (PMID 35655142, 2022). "We also detected rare genetic germline variants in DNA repair genes (e.g., BARD1, BRCA2, CHEK2, and WRN) that might cooperate with somatically acquired variants in these patients with highly aggressive recurrent neuroblastoma." (PMID 33384420, 2020).
neuroblastoma (continued). "Higher expression of CCNE1, CDK2 or CHEK2 was an unfavourable prognostic factor, while higher expression of SESN1 was a favourable prognostic factor in paediatric neuroblastoma." (PMID 35655142, 2022). "The results were consistent with overexpression of CCNE1, CDK2 or CHEK2 being worse prognostic factors, while increased regulation of SESN1 was a better prognostic factor in paediatric neuroblastoma." (PMID 35655142, 2022). "In contrast to CCNE1, CDK2 and CHEK2, SESN1 had opposite expression levels and prognostic effects in paediatric neuroblastoma." (PMID 35655142, 2022). "The Kaplan–Meier survival analysis further showed that overall survival was decreased in paediatric neuroblastoma patients with high CCNE1, CDK2 or CHEK2 expression." (PMID 35655142, 2022). "A majority of FOXM1 target genes, including CDC25B, CHEK2, CENPA, CENPB, and CENPF, were significantly downregulated in neuroblastoma cells with MEIS2 depletion." (PMID 25210800, 2014). "However, the prognostic effects of CCNE1, CDK2, CHEK2 and SESN1 were different in paediatric neuroblastoma." (PMID 35655142, 2022). "The mRNA expression levels of CCNE1, CDK2, CHEK2 and SESN1 in paediatric neuroblastoma patients with or without MYCN amplification were also investigated." (PMID 35655142, 2022). "However, the prognostic value of CHEK2 and SESN1 in paediatric neuroblastoma has never been reported." (PMID 35655142, 2022).